TEX9 (testis expressed 9)
Tractability: PROTAC: ubiquitination databases record sites on it.
Gene: Protein-coding gene on chromosome 15 (56,243,971 to 56,445,997, forward strand). Ensembl gene ENSG00000151575.
Subcellular location: Cytoplasm, cytoskeleton, microtubule organizing center, centrosome, centriolar satellite
Subcellular location (Human Protein Atlas): Centrosome; Cytosol; Primary cilium; Basal body; Nucleoli fibrillar center; Nucleoplasm; Vesicles
Gene Ontology:
Molecular function: protein binding
Cellular component: centriolar satellite
Genetic constraint (gnomAD): Loss-of-function variants: 43 observed, 39.83 expected, observed/expected ratio (o/e) 1.08, 90% interval 0.85 to 1.39. The upper end of that interval is the gene's LOEUF score, 1.39, which puts it in group 5 of 6, group 1 being the genes least tolerant of losing a copy. Missense variants: 393 observed, 348.96 expected, observed/expected ratio (o/e) 1.13, 90% interval 1.04 to 1.22. Synonymous variants: 143 observed, 121.36 expected, observed/expected ratio (o/e) 1.18, 90% interval 1.03 to 1.35.
Homologues: Orthologues: macaque TEX9 (92% identical), chimpanzee TEX9 (91% identical), rabbit TEX9 (86% identical), pig TEX9 (85% identical), dog TEX9 (83% identical), mouse Tex9 (76% identical), rat Tex9 (76% identical), guinea pig TEX9 (66% identical), tropical clawed frog tex9 (61% identical), zebrafish tex9 (50% identical), Drosophila melanogaster CG4681 (20% identical).
Diseases named in the same sentence as TEX9 in open-access papers:
TEX9 is named in the same sentence as 5 diseases in open-access papers, as found by Europe PMC text mining. Sharing a sentence is not in itself a finding about the gene and the disease. The quoted sentences say what the papers report.
cancer (3 papers, 2019 to 2022). A tumor composed of atypical neoplastic, often pleomorphic cells that invade other tissues. "TEX9 expression can be induced in tumor cells when cancer occurs." (PMID 36713586, 2022). "Moreover, the Tex261 family contains many members, among which Tex9 is believed to cooperate with eIF3b to promote proliferation and inhibit apoptosis of esophageal squamous cells and carcinoma occurrence by activating the AKT signaling pathway." (PMID 36408272, 2022).
tumor (2 papers, 2019 to 2022). "Also, according to the TCGA dataset, TEX9 expression level was positively correlated with the tumor differentiation." (PMID 31481019, 2019). "Limited research has revealed that TEX9 participated in tumor progression." (PMID 31481019, 2019). "The tumor xenograft assay also showed that si-Control groups could form significantly larger tumors than the SKD groups did, which indicated that knockdown of TEX9 significantly inhibited the proliferative ability of ESCC cells in vivo." (PMID 31481019, 2019).
TEX9 also shares sentences with these, for which no sentence is quoted: esophageal squamous cell carcinoma (2 papers); ciliopathies (1); lymphoma (1).